CD74 (CD74 molecule)
Diseases named in the same sentence as CD74 in open-access papers (continued):
Sharing a sentence is not in itself a finding about the gene and the disease.
COVID-19 (continued). "This strong increase in CD74 expression on CD8+ T cells during COVID-19 was found in virtually all analyzed patients, and was also demonstrated for the cell populations EM (mean: 4.0% on day 1, 50.0% on day 7) and E (mean: 1.9% on day 1, 40.2% on day 7)." (PMID 37946732, 2023). "Our study shows a concordant reduction in both serum levels and PBMCs expression levels of CD74 in COVID-19 patients, particularly those with severe disease." (PMID 37568438, 2023). "Further studies are needed to fully elucidate the mechanisms underlying these observations and to explore the potential therapeutic value of targeting CD74 and IL-13 in COVID-19." (PMID 37568438, 2023). "We investigated the levels of CD74 and D-DT in the sera of COVID-19 patients and healthy donors by ELISA." (PMID 37568438, 2023). "In this study, we investigated the involvement of CD74 and D-DT in COVID-19 patients with different disease severities, by employing an in silico analysis of a publicly available transcriptomic dataset and by measuring their serum levels by ELISA." (PMID 37568438, 2023). "Significantly lower levels of CD74 were observed in mild and moderate COVID-19 patients, as compared to healthy donors." (PMID 37568438, 2023). "Analysis of absolute numbers of CD8+ T cell subsets in the blood showed a reduction in CD74+ cell counts naive and TM phenotypes, but increased numbers of CD74+ EM and E cells in COVID-19 patients (Supplement 3B)." (PMID 37946732, 2023). "For CD4+ T cells, an increase in frequencies of CXCR2+ CD74+ cells was found in both mild and severe COVID-19 compared to healthy controls (mean: healthy: 17.7%, mild 46.9%, severe 42.9%)." (PMID 37946732, 2023). "These cell adhesion molecules (ANXA1 and ICMA2), cytokine binding and receptor activity genes (CD44, CD45, CD47, CD74, and THBS1), and inflammatory genes (FPR1 and SELL) have been reported to be associated with COVID-19." (PMID 35172892, 2022). "In line with the specific immune suppressive Mo-MDSC gene-expression pattern, MHC class II and CD74 were found at lower levels in severe COVID-19 patients compared to controls." (PMID 33479167, 2021). "Based on our results and the literature, we suggest that controlling the molecular interplay in Subnetwork 1 (i.e., the interplay between HLA class II, CIITA, and CD74) and the enriched pathways provides crucial clinical insights into the mechanism of COVID-19 severity." (PMID 40163554, 2025). "Although many studies have focused on the association between HLA class II and COVID-19, our results suggest that the interplay between HLA class II and its regulator and/or target genes (e.g., CIITA and CD74) may play a crucial role in COVID-19 severity." (PMID 40163554, 2025). "Our results suggest that the suppression or activation (or both) of the interplay between HLA class II, CIITA, and CD74 may provide crucial clinical insights for understanding the mechanism of COVID-19 severity." (PMID 40163554, 2025). "We speculate that the observed upregulation of CD74 reflects increased COVID-19-induced T-cell activation states, which might enhance susceptibility towards MIF." (PMID 38992165, 2024). "However, suitability of T-cell CD74 as a potential biomarker for disease progression in COVID-19 and its relevance in other inflammatory or malignant diseases accompanied by broad T-cell activation still needs to be evaluated in future prospective trials." (PMID 38992165, 2024). "Changes in the AS patterns of CD74 during infection, such as in COVID-19 patients, may impact the presentation of antigens and subsequently influence immune responses." (PMID 38414855, 2024). "Taken together, COVID-19 is associated with an enhanced expression of the MIF receptor CD74 on total CD4+ and CD8+ T cells independent of the disease severity." (PMID 37946732, 2023). "During COVID-19, T cells show an enhanced expression of CD74." (PMID 37946732, 2023).
COVID-19 (continued). "For CD8+ T cells, the CD74 molecule in combination with differentiation markers may be suitable as a biomarker for activated and possible harmful effector T cells in COVID-19 pathology." (PMID 37946732, 2023). "Similarly, CD74 was significantly lower in severe COVID-19 cases, while only a trend of reduction was found in the PBMCs collected from patients with moderate disease." (PMID 37568438, 2023). "We next aimed to investigate whether there were differences in the serum levels of D-DT and CD74 between recovered cases and lethal cases of severe COVID-19 patients." (PMID 37568438, 2023). "Thus, in COVID-19 patients, CD74+ T cells more frequently produce cytotoxic molecules in comparison to their CD74- counterparts." (PMID 37946732, 2023). "However, frequencies of CM, EM, and E convCD4+ T cells expressing CD74 significantly increased from day 1 to 7 post hospital admission in COVID-19, highlighting the importance of a sub-population-specific assessment." (PMID 37946732, 2023). "We observed that higher frequencies of T cells from patients with severe COVID-19 expressed CD74." (PMID 37946732, 2023). "In the present study, we aimed to investigate the potential involvement of CD74 and D-DT and their receptors in COVID-19 patients with different disease severity, by employing an in silico analysis of a publicly available transcriptomic dataset and by measuring their serum levels by ELISA." (PMID 37568438, 2023). "Interestingly, when analyzing absolute numbers of CD4+ T cell subpopulation, we observed significantly increased numbers of TM and EM convCD4+ T cells expressing CD74 in the blood of COVID-19 patients (Supplement 3A), despite their lymphopenia." (PMID 37946732, 2023). "In contrast, the expression of CXCR2 on CD74+ Tregs (mean: healthy 15.9%, mild 37.5%, severe 42.4%) as well as on CD74+ convCD4+ T cells (mean: healthy 16.3%, mild 42.1%, severe 39.1%) was enhanced in COVID-19 patients." (PMID 37946732, 2023). "COVID-19 is a dynamic disease with diverse outcomes, and studying patients over a longer period would provide a more comprehensive understanding of the involvement of CD74 and D-DT in different disease stages." (PMID 37568438, 2023). "Finally, using a Bayesian Network model, we identified FOS, CXCL8, IL1β, CST3, PSAP, CD45 and CD74 as predictors of the COVID-19 disease." (PMID 36532041, 2022). "Importantly, above immune findings were used for a Bayesian network model, which significantly revealed FOS, CXCL8, IL1β, CST3, PSAP, CD45 and CD74 as COVID-19 severity predictors." (PMID 36532041, 2022). "For example, isoform 001–004 of CD74 are down-regulated in the COVID-19 patients." (PMID 35421082, 2022). "B cells in PP of COVID-19 patients expressed lower levels of CD74 than in controls." (PMID 35251032, 2022). "CD74 also has immune-suppressant role, often observed in severe COVID-19 patients." (PMID 36532041, 2022). "Furthermore, the interplay between HLA class II, CIITA, and CD74 may play a key role in the severity of COVID-19." (PMID 40163554, 2025). "It is also interesting to note that in the transcriptomic studies, the significantly reduced expression of the MIF co-receptor CXCR4 paralleled that of CD74, suggesting that a common mechanism of downregulated expression could occur during moderate and severe cases of COVID-19." (PMID 37568438, 2023). "Furthermore, we aimed to determine whether there were correlations between the levels of D-DT and CD74 and other investigated cytokines and blood cell counts in severe cases of COVID-19." (PMID 37568438, 2023). "Besides, CD74 is known to have increased expressed in the severe COVID-19 patients." (PMID 36532041, 2022). "Our strategy revealed COVID-19 severe specific molecular interplays between HLA class II and CIITA/CD74, those cannot be revealed by the single gene-based existing studies." (PMID 40163554, 2025).
COVID-19 (continued). "Overall, we confirmed an upregulation of the MIF receptor CD74 in CD4+ and CD8+ T cells in critically ill COVID-19 patients." (PMID 38992165, 2024). "Therefore, MIF and CD74 might become targets for COVID-19 treatment." (PMID 37853311, 2023). "CD74, CIITA, CD3D and IL7R were downregulated in critically ill COVID-19 patients in accordance with the occurrence of altered monocyte and T lymphocyte responses." (PMID 36389738, 2022). "We did not observe any significant alteration in the expressions of CD74 and LYN in the whole blood of hospitalized COVID-19 patients compared to the Healthy group." (PMID 36611805, 2022). "CD74 is involved in MHC Class-II mediated antigen presentation, a process upregulated in the COVID-19 patients." (PMID 36532041, 2022). "Considering the significant depletion of GC and reduced T cell/B cell interaction in the ileal follicles in PP of COVID-19 patients, we next evaluated the CD27 and CD74 expression by B cells." (PMID 35251032, 2022). "Just like CD74, CD45 is also an immune-suppressant, and therefore enhanced expression in the severe COVID-19 patients." (PMID 36532041, 2022). "Specifically, in the COVID-19 patient’s B cells, we detected a substantial increase in the expression of CD52, CD74, CD22 and CD79B and a decrease in CXCR4, CD69, INFGR1, PTPRC and LAMP1 transcripts with respect to control-derived B cells." (PMID 34944610, 2021). "Performing this analysis for the COVID-19 patients demonstrated clear B- and T-cell clusters, defined by expression of TCF7, LEF1 (clusters 0 and 1), CD74, CD79A (clusters 2 and 3), IL7R (cluster 4) and CCL5, NKG7, GNLY (cluster 6)." (PMID 33884369, 2021). "Upon SARS-CoV-2 infection, frequencies of CD74-expressing CD4+ T cells from COVID-19 patients with a mild disease course were not altered in comparison to healthy individuals." (PMID 37946732, 2023). "In order to determine which subpopulations of CD8+ T cells might be responsive to MIF during COVID-19, the expression of CXCR2 and CXCR4 on CD74+ CD8+ T cells was analyzed." (PMID 37946732, 2023). "We found that MIF was DEG and CD74 was both DDG and ‘dark’ gene, which indicated that the combination of DEGs and DDGs could be better used to study COVID-19 in depth." (PMID 37853311, 2023). "The interaction between CD74 and MIF may be involved in regulating the inflammatory response in COVID-19 patients, affecting the activation of immune cells and the release of inflammatory mediators." (PMID 37853311, 2023). "Significantly increased percentages of CXCR4-expressing CD74+ CD4+ T cells (mean: healthy 61.5%, mild 84.0%, severe 81.0%) and CXCR4 CD74+ CD8+ T cells (mean: healthy 54.2%, mild 78.4%, severe 71.7%) were observed in both groups of COVID-19 patients in comparison to healthy controls." (PMID 37946732, 2023). "While this study hints for the first time at the involvement of CD74 and D-DT in COVID-19, there are some limitations that do not allow to establish more robust conclusions regarding the role of these factors in disease severity and treatment." (PMID 37568438, 2023). "In contrast to COVID-19(+) TV, highly expressed in the COVID-19(-) PU control group included MHC class II antigen processing (HLA-DRB3/4, HLA-DPB1, HLA-DRA, CIITA, and CD74), mast cell degranulation (TPSAB1/B2), B cell activation (CXCL13, BLNK, IL-6) and histone modification (USP21, HIST1H4E)." (PMID 37026002, 2023). "The negative correlation between CD74 serum levels and IL-13 found in our study suggests a potential role of CD74 in regulating the IL-13-mediated immune response and inflammation in COVID-19." (PMID 37568438, 2023). "The majority of CD74+ convCD4+ T cells at all stages of differentiation co-expressed the CXCR4 molecule, but increased frequencies of CXCR4+ CD74+ convCD4+ T cells in COVID-19 were only detected in cells with a naïve phenotype (mean: healthy 83.8%, mild: 82.1%, severe: 93.3%)." (PMID 37946732, 2023).
COVID-19 (continued). "For example, increased expressions of IL10, IL1R2 mRNA and decreased expression of CD74 and CIITA mRNA were described in monocytes of progressive COVID-19 patients compared with stable patients suggesting the acquisition of a regulatory phenotype by myeloid cells." (PMID 36389738, 2022). "In addition, we deployed validation experiments for local splicing changes of 6 genes (CD74, LRRFIP1, SH3GLB1, MACF1, RPS24 and PDLIM5) between 9 COVID-19 cases and 10 controls by semiquantitative reverse transcription (RT)-PCR." (PMID 35421082, 2022). "However, in the severe and convalescence from moderate conditions, the most active multi-receptor unit is the heteromeric complex containing CD74 and CXCR4, indicating differences in the types of MIF-specific interactions across COVID-19 conditions." (PMID 36105110, 2022). "Notably, CD74 and LRRFIP1 had increased skipping of an exon in COVID-19 patients that disrupts a functional domain, which correlated with reduced antiviral immunity." (PMID 35421082, 2022). "In contrast, genes involved in antigen presentation through MHC II presented a “valley” pattern, with under-expression among TUBE early compared to HLTY and COVID-19 compared to INFL, which strikingly predominated in TUBE early (e.g. HLA-DRA, HLA-DRB1, HLA-DQA1, CD74/Ii/CLIP/SLIP)." (PMID 34135895, 2021). "In detail, transmembrane receptor CD74 and TLR-4, -5, and -8, which were shown to be upregulated in response to neutrophil stimulation and to trigger neutrophil IL-8 production, were increased in patients with severe COVID-19." (PMID 34403366, 2021). "Blood was drawn from hospitalized patients with mild and severe COVID-19 within the first 24 hours after admission to the hospital (day 1) as well as on the seventh day of hospitalization (day 7), and isolated T cells were analyzed for the expression of the MIF receptor CD74." (PMID 37946732, 2023). "Furthermore, we observed a negative correlation between CD74 serum levels and IL-13, a cytokine that has been recently described to be pathogenetic in COVID-19." (PMID 37568438, 2023). "Despite these limitations, the present study, for the first time, provides insight into the role of CD74 and D-DT in the immune response to SARS-CoV-2 infection and highlights the potential for these proteins to be targeted in the development of new therapies for COVID-19." (PMID 37568438, 2023). "We speculate that IL17RD, CD74, and TNFSF15 may serve as disease biomarkers in COVID-19." (PMID 36483456, 2022). "Thus, we speculate that IL-17RD, CD74, and TNFSF15 might serve as disease biomarkers for COVID-19." (PMID 36483456, 2022).
lymphoma (20 papers, 2010 to 2026). A malignant (clonal) proliferation of B- lymphocytes or T- lymphocytes which involves the lymph nodes, bone marrow and/or extranodal sites. "Given the usually limited prognosis of subgroups of these lymphoma entities and of relapsed and refractory disease, CD74 and its associated signaling components represent promising candidates for the development of new therapeutic strategies for these T cell-derived malignancies." (PMID 34638496, 2021). "Despite these setbacks, milatuzumab has remained an important proof-of-concept molecule and has informed the design of next generation CD74-directed ADCs and combination regimens for leukemia, lymphoma, and other diseases." (PMID 41597203, 2026). "An advanced allogeneic CD19‐CAR iNKT product co‐expressing IL‐15 and shRNAs against B2M/CD74 (to reduce HLA‐I/II expression) demonstrated efficacy in R/R non‐hodgkin lymphoma and acute lymphoblastic leukemia." (PMID 41292193, 2025). "This perturbation increases tumor aggressiveness of IRF8-mutant lymphomas, which is clinically and immunologically corrected by CD74 expression or anti–PD-L1 treatment." (PMID 38996030, 2024). "Mice harboring IRF8-mutant lymphomas displayed larger tumor burden, in association with remodeling of the TME, an immunophenotype that was rescued in vivo by ectopic expression of CD74 and validated in primary human DLBCLs." (PMID 38996030, 2024). "We previously reported that CD74 interferes with the expression of the FAS receptor on the surface of lymphoma cells." (PMID 39056676, 2024). "Only recently, CD74 expression has been analyzed on a broad lymphoma panel including B and T cell lymphoma subtypes." (PMID 34638496, 2021). "In contrast to B cells, T cells usually lack CD74 expression, and CD74 has previously been reported only on cutaneous T cell-derived lymphoma cell lines as well as certain T cell subsets following activation." (PMID 34638496, 2021). "We conclude that CD74 regulates Fas death receptor signaling in lymphomas by decreasing the levels of Fas receptor on the cell surface." (PMID 25304249, 2014). "In the presented study we evaluated the effect of CD74 on the Fas-mediated apoptotic signaling in lymphoma cells by knocking down the expression of CD74 in BJAB and Raji human NHL cells." (PMID 25304249, 2014). "It is noteworthy that both the GBM and lymphoma hybrid transplants all retained CD74, CXCR4 and VIM genes, suggesting that these are important to evaluate in other examples of spontaneous fusions of human tumor and rodent host cells." (PMID 23405135, 2013). "Several lymphoma subtypes exploit CD74-related mechanisms to evade immune surveillance." (PMID 41597203, 2026). "For example, upregulated proteins such as HLA-DRB1, CD22, CD74, and CD8A are consistent with established roles in lymphoid malignancies and oncogenic signaling, supporting prior studies identifying CD74 as a diagnostic and therapeutic target in lymphomas." (PMID 41035678, 2025). "A Expression of CD74 (gray) on MCL patients’ lymphoma cells compared to isotype control (white)." (PMID 37740214, 2023). "Moreover, genes encoding CD74 and IL4R are expressed in lymphoma biopsies isolated from all stages of disease." (PMID 36353222, 2022). "CD74 expression in T cell-derived malignancies has been previously reported for one Sézary syndrome cell line, and only recently has CD74 been analyzed in various lymphoma subtypes including T cell-derived malignancies." (PMID 34638496, 2021). "Notably, the same CpGs showed decreased DNA methylation in several primary ALCL samples and ALCL cell lines compared to normal T-cell subsets, further supporting unusual CD74 expression in this putative T cell-derived lymphoma entity." (PMID 34638496, 2021). "The bispecific anti-CD20/anti-CD74 antibody has been tested in mantle cell lymphoma, an NHL sub-type and has significantly improved survival of mice with lymphoma." (PMID 36353222, 2022).